PTP4A3 (protein tyrosine phosphatase 4A3)
Diseases named in the same sentence as PTP4A3 in open-access papers (continued):
Sharing a sentence is not in itself a finding about the gene and the disease.
tumor (25 papers, 2009 to 2025). "Protein tyrosine phosphatase 4A3 (PTP4A3) overexpression is implicated in tumour cell invasion and metastasis by upregulating the PI3K/Akt/mTORC1 axis." (PMID 40657934, 2025). "PTP4A3 is highly expressed in the tumor-associated endothelium, which has a central role in metastases formation and angiogenesis." (PMID 29492190, 2018). "Considerable evidence suggests a causal role for PTP4A3 in tumor metastasis but little is known about PTP4A3-mediated cellular signaling pathways." (PMID 24376839, 2013). "Loss of CDKN2B and gain of BCL6, FGF3, and PTP4A3 predicted tumor." (PMID 22570652, 2012). "Previous studies have revealed several abnormally expressed genes in NPC that could serve as reliable prognostic factors, like H3K27me3, ULK1, LOX, Talin-1 and PTP4A3, however, the existing molecular markers are substantially limited in identifying tumor spread and aiding risk assessment." (PMID 29100406, 2017). "Overexpression of PTP4A3 mRNA in OC has been detected in advanced stage‐III when compared to early stage‐I tumours, suggesting a correlation between PTP4A3 mRNA and protein expression and the invasiveness of OC." (PMID 40657934, 2025). "We determined the correlation between PTP4A3 and TIDE, dysfunction, exclusion, myeloid-derived suppressor cells (MDSSs), CAFs, and tumor-associated macrophage (TAM).M2 scores obtained for different datasets." (PMID 36213837, 2022). "The results reveal that the expression of PTP4A3 correlates significantly with disease prognosis and the tumor microenvironment." (PMID 36213837, 2022). "The expression levels of the LIHC and adjacent samples were analyzed, and it was observed that the expression level of PTP4A3 in tumor tissue was significantly higher than the expression level of the same gene in the adjacent samples." (PMID 36213837, 2022). "We utilized the Oncomine and Tumor Immunoassay Resource databases to examine the differential expression of PTP4A3 in tumor tissues and normal tissues in breast, urinary tract, gastrointestinal tract and skin." (PMID 34630392, 2021). "PTP4A3 promotes the proliferation, migration, and invasion of tumor cells by activating the Rho family and matrix metalloproteinase-2." (PMID 34630392, 2021). "PTP4A3-zumab recruited B cells, NK cells and macrophages to the PTP4A3+ tumor cells in an FcR-dependent manner." (PMID 34630392, 2021). "We previously reported that PTP4A3 was overexpressed in human OvCa tumor samples but the involvement of PTP4A3 in HGSOC is less well understood." (PMID 34209460, 2021). "Efforts to uncover the biochemical functions of PTP4A3 and credential it as a high-value tumor target have been hampered due to the dearth of potent and selective inhibitors of PTP4A3." (PMID 34209460, 2021). "RhoA activation is known to be integral to the promotion of growth, migration, and dissemination of tumor cells, and elevated PTP4A3 expression levels are reported to alter RhoA activity." (PMID 29492190, 2018). "Immunohistochemical analysis of human patient tumor samples from the University of Virginia Biorepository revealed PTP4A3 protein overexpression in 45/57 (79%) primary OvCa tumors, as well as in the tumor endothelium and pericytes." (PMID 29492190, 2018). "While considerable heterogeneity in Ptp4a3 expression was observed, ranging from 1.4 to 6.7-fold upregulation, Ptp4a3 mRNA levels in tumor tissue were consistently higher than normal tissue for every sample tested (n = 15)." (PMID 23555575, 2013).
tumor (continued). "While the Ptp4a3 gene product initially was thought to be involved in tumor metastasis and late stage disease, our results provide evidence for possible roles at other stages of the disease including pre-neoplastic transformation and early carcinogenesis." (PMID 23555575, 2013). "The OS was statistically significantly correlated with seven factors such as AST, serum AFP, tumor size, tumor differentiation, portal vein invasion, stage of tumor, and PTP4A3/PRL-3 expression." (PMID 23064776, 2013). "The resulting tumor tissue had 4-fold more Ptp4a3 mRNA relative to normal colon epithelium and increased PTP4A3 protein." (PMID 23555575, 2013). "The animal model we have developed presents a unique opportunity to address the role of Ptp4a3 in tumor biology." (PMID 23555575, 2013). "Despite the apparent importance of Ptp4a3 in tumor biology, our understanding of the functionality of Ptp4a3 is severally limited due in part to the absence of informative animal models." (PMID 23555575, 2013). "Three of these, i.e., Lrmp, Hcls1 and Prkrir, were up regulated and one, i.e., Ptp4a3, was down regulated in the affected tumor." (PMID 22028901, 2011). "Finally, we considered the reported roles of PTP4A3 in tumour recurrence and chemotherapy resistance, where its mRNA and protein expression are upregulated following exposure to chemotherapeutic drugs." (PMID 40657934, 2025). "Recent studies report a physiological role for PTP4A3 and 1 protein in regulating micropinocytosis via its lipid phosphatase activity, suggesting that tumour cells may exploit this mechanism to survive in nutrient‐deprived microenvironments." (PMID 40657934, 2025). "We first assessed the expression level of PTP4A3 in tumor and normal (tumor-adjacent) samples." (PMID 36213837, 2022). "Moreover, PTP4A3 contributes to the secretion of inflammatory factors, which recruit more immune cells to the tumor microenvironment." (PMID 34630392, 2021). "IL-6 has been reported to induce PTP4A3 expression and to promote OvCa tumor cell migration." (PMID 34209460, 2021). "The screen standard was defined as Cor>0.2, P<0.05 to identify PTP4A3-associated immune cell markers with or without tumor purity adjustment in KIRP and KIRC." (PMID 34630392, 2021). "Interestingly, LUAD was the only tumor type in which low PTP4A3 expression was correlated with decreased DFS." (PMID 34630392, 2021). "Expression of PTP4A3 were obviously higher in tumor tissue compare with normal tissues (P=0.028)." (PMID 34630392, 2021). "PTP4A3 expression in diverse tumor types was further assessed using the TCGA and TIMER databases." (PMID 34630392, 2021). "Additionally, PTP4A3 (PRL-3) has been reported to trigger tumor angiogenesis through the recruitment of endothelial cells." (PMID 31035605, 2019). "Thus, targeting PTP4A3, upstream of RhoA, can have multi-faceted anti-tumor and anti-metastatic effects." (PMID 29492190, 2018). "Previous studies have showed that up-regulation of the PRLs, especially PTP4A1 and PTP4A3 could promote cell invasion, migration and metastasis during tumor development and progression." (PMID 29100406, 2017). "Ptp4a3-null mice exhibit a 54% decrease in tumor number (p<0.004) following 16 wk of treatment." (PMID 23555575, 2013). "Therefore, PTP4A3 phosphatase appears to influence the function of both tumor and stromal cells." (PMID 29492190, 2018). "Additionally, ectopic PTP4A3 overexpression enhances tumor cell migration and invasion in vitro." (PMID 23555575, 2013). "Then we injected the stable cell lines containing m3E sgRNAs for CBX8, CCND1, PTP4A3, RPS6KA5 and TNFSF10 into nude mice and checked whether tumor growth was repressed." (PMID 38012744, 2023). "In KIRC, we observed negative association between PTP4A3 expression and the density of CD3+ TILs intratumor and CD8+ TILs intratumor in the tumor microenvironment." (PMID 34630392, 2021).
tumor (continued). "Research with target monoclonal antibodies and DNA vaccines has indicated that PTP4A3 may collaborate with CTL and Th1 cells in the tumor microenvironment." (PMID 34630392, 2021). "Interestingly, the number of tumors (p = 0.05) as well as tumor diameter (P<0.001) was significantly increased from 12 to 16 wk, while Ptp4a3-null tumors did not significantly increase in number or size." (PMID 23555575, 2013).
adenocarcinoma (1 paper, 2022). A common cancer characterized by the presence of malignant glandular cells. "To conclude, our comprehensive analyses identified PTP4A3, NAPRT, and RECQL4 were co-amplified and co-expressed specifically in LEP/MIP adenocarcinoma, and RECQL4 was upregulated in the MIP group." (PMID 35992814, 2022).
colon (1 paper, 2013). "Following quantification, IGF1Rβ protein was on average 2.1-fold higher (p<0.001) and c-MYC was about 2.5-fold higher (p<0.02) in Ptp4a3-null relative to wildtype colon tumors." (PMID 23555575, 2013).
epithelial neoplasm (1 paper, 2023). A benign or malignant neoplasm that arises from and is composed of epithelial cells. "Protein tyrosine phosphatase 4A3 (PTP4A3) is a subclass of the protein tyrosine phosphatase super family and is expressed in a range of epithelial neoplasms." (PMID 38187082, 2023).
infection (1 paper, 2019). The state of being infected such as from the introduction of a foreign agent such as serum, vaccine, antigenic substance or organism. "To determine whether the function of CRMP2 is required for the PTP4A3-associated pro-migratory and invasive phenotypes of UM cells, we performed RNA interference experiments by lentivirus shRNA anti-CRMP2 infection." (PMID 30816227, 2019).
PTP4A3 also shares sentences with these, for which no sentence is quoted: non-small cell lung carcinoma (3 papers); colitis (2); glioblastoma (2); multiple myeloma (2); rectal adenocarcinoma (2); thyroid cancer (2); acute lymphoblastic leukemia (1); bladder cancer (1); cholangiocarcinoma (1); clear cell renal cell carcinoma (1); colon adenocarcinoma (1); colorectal tumors (1); eye cancer (1); HTLV infection (1); intestinal tumor (1); lung adenocarcinoma (1); lymph node metastasis (1); metastasis (1); metastatic colorectal cancer (1); Myelodysplasia (1); myeloid neoplasm (1); myeloproliferative disorder (1); neutropenia (1); osteosarcoma (1); pancreatic cancer (1); prostate adenocarcinoma (1); prostate tumors (1); sarcoma (1); serous cystadenocarcinoma (1); skin cancer (1).
A further 4 diseases each share a sentence with PTP4A3 in 1 paper.